SLK (STE20 like kinase)
Description:
Mediates apoptosis and actin stress fiber dissolution.
Synonyms: KIAA0204; STK2; se20-9; LOSK; bA16H23.1
Tractability: Small molecule: a structure with a bound ligand is known; a high-quality ligand is known; it has a binding pocket of medium quality; it belongs to a druggable protein family. Antibody: the Human Protein Atlas places it where antibodies can reach. PROTAC: ubiquitination databases record sites on it; its protein half-life has been measured; a small molecule that binds it is known.
Target class: STE protein kinase SLK subfamily; STE protein kinase STE20 family; STE protein kinase group; Kinase; Enzyme; Protein Kinase
Gene: Protein-coding gene on chromosome 10 (103,966,916 to 104,029,242, forward strand). Ensembl gene ENSG00000065613.
Subcellular location: Cytoplasm
Subcellular location (Human Protein Atlas): Cytosol; Plasma membrane
Pathways (Reactome):
Signal Transduction: RHOA GTPase cycle; RHOB GTPase cycle; RHOC GTPase cycle
Gene Ontology:
Molecular function: cadherin binding; identical protein binding; protein binding; protein homodimerization activity; protein serine/threonine kinase activity; ATP binding; protein kinase activity; protein serine kinase activity
Biological process: cytoplasmic microtubule organization; protein autophosphorylation; regulation of apoptotic process; regulation of cell migration; regulation of focal adhesion assembly; intracellular signal transduction
Cellular component: cytoplasm; extracellular exosome; perinuclear region of cytoplasm; cell leading edge; cytosol
Genetic constraint (gnomAD): Loss-of-function variants: 56 observed, 114.04 expected, observed/expected ratio (o/e) 0.49, 90% interval 0.4 to 0.61. The upper end of that interval is the gene's LOEUF score, 0.61, which puts it in group 2 of 6, group 1 being the genes least tolerant of losing a copy. Missense variants: 940 observed, 1,232 expected, observed/expected ratio (o/e) 0.76, 90% interval 0.72 to 0.81. Synonymous variants: 356 observed, 409.04 expected, observed/expected ratio (o/e) 0.87, 90% interval 0.8 to 0.95.
Homologues: Orthologues: chimpanzee SLK (99% identical), macaque SLK (97% identical), dog SLK (91% identical), pig SLK (90% identical), rabbit SLK (89% identical), guinea pig SLK (84% identical), mouse Slk (84% identical), rat Slk (82% identical), tropical clawed frog slk (66% identical), zebrafish slka (60% identical), zebrafish slkb (56% identical). Paralogues in human: STK10 (44% identical), TNIK (23% identical), MAP4K4 (22% identical), MINK1 (21% identical), TAOK1 (20% identical), TAOK3 (19% identical), TAOK2 (19% identical), NRK (17% identical), MAP4K3 (17% identical), MAP4K5 (16% identical), MAP4K2 (16% identical), MAP4K1 (14% identical), and 23 more.
Diseases named in the same sentence as SLK in open-access papers:
SLK is named in the same sentence as 20 diseases in open-access papers, as found by Europe PMC text mining. Sharing a sentence is not in itself a finding about the gene and the disease. The quoted sentences say what the papers report.
breast carcinoma (8 papers, 2017 to 2024). "Together, these studies suggest that the loss of SLK results in the activation of Sox9 that can directly induce Sox10 expression in murine tumors as well as human breast cancers." (PMID 33985544, 2021). "SLK has been reported to associate with blood cancer, breast cancer, colorectal cancer, liver cancer, and pancreatic cancer." (PMID 32300588, 2020). "Emerging evidence suggests that SLK plays important roles in cancer; for instance, loss of SLK in a murine model of HER2/Neu-positive breast cancers accelerates tumour onset and decreases overall survival." (PMID 39660256, 2024). "Metastatic samples showed SLK overexpression in our study, something that has been previously observed in other cancer types such as ErbB2-driven breast cancer." (PMID 35560144, 2022). "Supporting a role for SLK in HER2-driven signaling, expression of a dominant negative SLK K63R reduced HER2-dependent chemotaxis in human breast cancer cell lines." (PMID 33985544, 2021). "As we have shown that AKT activity is required for maintenance of Sox10 expression in SLK knockout mammary tumor cells, we first assessed the levels and nuclear localization of known transcription factors that are AKT-responsive." (PMID 33985544, 2021). "SLK knock down was previously shown to inhibit heregulin-driven invasion in breast cancer cells." (PMID 29228724, 2017). "Because of our interest the response of mammary epithelium and breast cancer cells to pro-invasive signals, we investigated whether SLK knockdown would also impair the increased motility phenotype associated with TGFβ-induced EMT." (PMID 29228724, 2017). "As SLK plays a role in cytoskeletal remodelling, cell migration and heregulin-induced invasion of breast cancer cells, we have tested the hypothesis that SLK is required for TGFβ-mediated EMT and the downstream cytoskeletal remodelling necessary to confer the invasive phenotype." (PMID 29228724, 2017). "We found several targets of QKI and RBFOX1, including FLNB, SLK, USO1, ENAH, ESYT2, NUMB and ARHGEF1, to be among the most differentially spliced genes in basal B breast cancer cell lines." (PMID 30059005, 2018). "Moreover, TET3 knocked-down cells under normoxia exhibited an identical alternative splicing pattern of ESRP1 targets (hMENA, SLK, SCRIB, RALGPS2, SLC37A2, FNIP1, CD44, and ARHGEF1) as the hypoxic breast cancer cells." (PMID 34362878, 2021).
liver cancer (2 papers, 2020 to 2023). An epithelial or non-epithelial malignant neoplasm that arises from the liver. "Among the three protein isoforms encoded by SLK, SEPepQuant connected this specific isoform to liver cancer development and prognosis, suggesting a critical pro-tumor role of the exon-skipping event." (PMID 37726316, 2023).
metastatic melanoma (2 papers, 2021 to 2022). A melanoma that has spread from its primary site to another anatomic site. "We demonstrate differential apoptosis and protein localization between SLK isoforms in metastatic melanoma." (PMID 35560144, 2022). "It appears that invasion is the functional benefit provided by SLK overexpression to metastatic melanoma." (PMID 35560144, 2022). "We wished to see if overexpression of the two SLK isoforms could produce cell death in metastatic melanoma." (PMID 35560144, 2022). "The SOX10 promoter has previously been shown to be epigenetically silenced in human gastric cancers and metastatic melanoma, the basal level of Sox10 expression is low in vitro, we hypothesized that Sox10 gene induction could be due to gene demethylation in SLK-/- NDL cells." (PMID 33985544, 2021).
acute kidney injury (1 paper, 2017). Sudden and sustained deterioration of the kidney function characterized by decreased glomerular filtration rate, increased serum creatinine or oliguria. "The characterization of the key SLK phosphorylation sites and regulation of catalytic activity may also provide novel targets for design of drugs, which may be useful in the treatment of acute kidney injury, glomerulonephritis, wound healing, cancer, and other diseases." (PMID 28475647, 2017).
endometrial cancer (1 paper, 2025). Primary or metastatic malignant neoplasm involving the endometrium (mucous membrane that lines the endometrial cavity). "To validate the differential expression of ZNF626, SLK, and RFWD3 proteins in endometrial cancer (EC), we compared their expression levels in EC tissues with those in normal endometrial tissues." (PMID 40002911, 2025). "Therefore, ZNF626, SLK, and RFWD3 may represent potential therapeutic targets for endometrial cancer." (PMID 40002911, 2025). "Although the roles of ZNF626, SLK, and RFWD3 in endometrial cancer have not been extensively discussed, their biological functions in relation to other tumors are well documented and can provide insights for our study." (PMID 40002911, 2025).
leiomyoma (1 paper, 2013). A well-circumscribed benign smooth muscle neoplasm characterized by the presence of spindle cells with cigar-shaped nuclei, interlacing fascicles, and a whorled pattern. "Chromosome 10q24.33 seems to have the best association with leiomyomas; the region was mapped to the 5′ region of the SLK gene encoding STE20-like kinase." (PMID 24163697, 2013).
lung carcinoma (1 paper, 2022). "Immunohistochemistry data of the three model gene proteins (MRPL51, SLK, PRC1) were retrieved from the HPA database and their expression was found to be upregulated in lung cancer." (PMID 35982906, 2022).
melanoma (1 paper, 2022). A malignant, usually aggressive tumor composed of atypical, neoplastic melanocytes. "Within the melanoma sequence data, we confirmed exon skipping in three genes–MAP3K3 (exon 3), FES (exon 11) and SLK (exon 13)." (PMID 35560144, 2022).
membranous nephropathy (1 paper, 2017). "To address SLK activation and phosphorylation in a pathophysiological context, we examined SLK activation in the PHN model of experimental membranous nephropathy, using quantitative immunofluorescence microscopy." (PMID 28475647, 2017).
renal carcinoma (1 paper, 2021). A carcinoma arising from the epithelium of the renal parenchyma or the renal pelvis. "However a subsequent study revealed SLK to be a contaminant from a renal carcinoma cell line, and the investigators noted its unsuitability for KSHV/endothelial biology and pathogenesis." (PMID 33937098, 2021).
cancer (10 papers, 2014 to 2025). A tumor composed of atypical neoplastic, often pleomorphic cells that invade other tissues. "In certain cancers, SLK overexpression has been associated with increased cell proliferation, protein reorganization in muscle tissue, and enhanced tumor invasion and metastasis." (PMID 40002911, 2025). "In order to further verify the close relationship of SLK and cancer, we checked the mutation of SLK in the COSMIC database, and found that missense substitution occurred in 36.93% of the samples." (PMID 32300588, 2020). "In particular, SLK was more likely to be cancer-related due to its high missense mutation rate and associated with cell adhesion." (PMID 32300588, 2020). "SLK was identified as a prognostic biomarker in several cancers and is necessary for the induction of cell migration and invasion during EMT." (PMID 33845831, 2021). "Promising new splice variants with a potential link with cancer are CSF1, PLOD2, SLK, SPAG9 and TSC2." (PMID 33845831, 2021). "Not only have we successfully verified that genes like EPRS were indeed related to various cancers, but also we found that genes such as SLK were related to survival of multiple cancers." (PMID 32300588, 2020). "Moreover, by comparing the 13 survival-related gene lists, seven genes (SLK, API5, BTBD2, PTAR1, VPS37A, EIF2B1, and ZRANB1) were found to be associated with prognosis in a variety of cancers." (PMID 32300588, 2020). "Surprisingly, a comprehensive analysis of 14 major carcinomas across 6586 patients revealed that epithelial tumors frequently harbor putative heterozygous deletions of RHOA, SLK, STK10, and ERM." (PMID 34635648, 2021). "It regulates the alternative splicing of cancer-related transcripts MDM4 and SLK in HCT116 cells." (PMID 36611187, 2023). "Similarly, RBM47-induced splicing changes were seen in genes such as SLK, MDM4 and TNC, all of which are genes with known functions in cancer." (PMID 24898756, 2014).
tumor (7 papers, 2017 to 2025). "Here, we have shown that the observed induction of Sox10 in SLK-/- NDL tumor cells is dependent on a novel enhancer located at about −7kb upstream of the putative Sox10 start site." (PMID 33985544, 2021). "Our data show that AKT can directly phosphorylate Sox9 in vitro at serine 181 and that AKT inhibition blocks Sox9 phosphorylation and Sox10 expression in SLK(-/-) tumor cells." (PMID 33985544, 2021). "Six have been indirectly linked to tumour malignancy and are thus new splicing targets to study (CAST, CSF1, PLOD2, SLK, SPAG9, TSC2)." (PMID 33845831, 2021). "Compared to healthy individuals, the expression levels of ZNF626 and SLK were elevated in EC patients, suggesting that these genes may promote tumor occurrence and development." (PMID 40002911, 2025). "Western blot analysis showed a marked increase in the levels of Sox9 S181 phosphorylation in SLK knockout tumor cell lines that was correlated with elevated Sox10 levels in these cells, suggesting increased Sox9 activity in SLK-null tumor cells compared to the control." (PMID 33985544, 2021). "Therefore, this exon skipping may lead to reduced SLK activity and decreased apoptosis to facilitate tumor progression." (PMID 37726316, 2023). "We observed a significant association between OS and the expression of six genes (CCNH, MLH3, RAD51C, RPA3, SLK, and XPA) in primary tumor tissues." (PMID 37240218, 2023). "In primary tumor tissue, the string correlations among CCNH, XPA, and SLK are interesting: CCNH and its correlation with CDK7 and, last but not least, the correlation of CDK7 in strings with RAD51C and XPA." (PMID 37240218, 2023). "Further relevance analysis between genes and immunization revealed a decreased proportion of memory CD4+ T cells in the tumor group, with RFWD3 positively correlating with M1 macrophages, ZNF626 positively correlating with M2 macrophages, and SLK negatively correlating with M1 macrophages." (PMID 40002911, 2025). "Estrogen promotes cell proliferation and inhibits apoptosis by upregulating ZNF626 and SLK genes and downregulating the RFWD3 gene, while also leading to a decline in memory CD4+ T cells and a shift in macrophage phenotypes from M1 to M2 within the tumor inflammatory microenvironment." (PMID 40002911, 2025).
myopathy (2 papers, 2017 to 2023). A disease of the muscle in which the muscle fibers do not function properly. "Our data show that the loss of SLK results in unstable myofibers resulting in a progressive myopathy." (PMID 28153048, 2017). "Taken together, our data suggest that the myopathy observed in the SLK-deficient muscles is due in part to underlying defects in the costamere or sarcomere organization due to altered localization of components of the focal adhesion complex." (PMID 28153048, 2017). "Especially, muscle‐specific SLK depletion in adult mice displays a progressive myopathy, manifesting with a progressive increase in muscular weakness and fatigue." (PMID 36579845, 2023). "Overall, our data show that deletion of SLK in myogenic precursors did not overtly affect muscle development but induced a mild myopathy that was readily apparent in older mice." (PMID 28153048, 2017). "Our data show that mice lacking SLK in skeletal muscles are viable and fertile but present with a progressive central nuclear myopathy and muscle weakness that is readily apparent as early as 3 months of age." (PMID 28153048, 2017).
SLK also shares sentences with these, for which no sentence is quoted: blood cancer (1 paper); colorectal cancer (1); gastric cancer (1); glioma (1); glomerulonephritis (1); myasthenia gravis (1); pancreatic cancer (1).